PARP1 (poly(ADP-ribose) polymerase 1)
Diseases named in the same sentence as PARP1 in open-access papers (continued):
Sharing a sentence is not in itself a finding about the gene and the disease.
breast cancer (continued). "In order to further understand the role of PARP1, XRCC4 and ERCC1 in predicting the prognosis, metastasis of breast cancer, we also studied the best cut-off value of PARP1, XRCC4 and ERCC1." (PMID 33184404, 2020). "Here we show that in the context of breast cancer, PARP1 can control inflammatory cytokine production in cancer cells." (PMID 32455851, 2020). "Results of our preclinical study on synergism between KLF4 and PARP1 have shed light on a novel therapeutic strategy for the BRCA1‐proficient population of TNBC breast cancer patients." (PMID 33231937, 2020). "There has been significant interest in PARP-1, and particularly PARP inhibitors, because of its synthetic lethal partnership with BRCA1/2 mutations in breast cancers." (PMID 35582232, 2020). "Elevated PARP-1 expression is always observed in many diseases, such as breast cancer, melanomas, and lung cancer." (PMID 32779949, 2020). "Several potential targets were subsequently identified and c-Met and poly (ADP-ribose) polymerase-1 (PARP-1) were manually chosen as the key targets in breast cancer." (PMID 32201536, 2020). "In cell experiments, Mk-4827, a PARP-1/2 inhibitor, promoted lung and breast cancer cell sensitivity to radiation." (PMID 32355263, 2020). "With both BRCA1m and PARP1m, the TNBC cells were more sensitive to three representative chemotherapeutic breast cancer drugs, doxorubicin, gemcitabine and docetaxel, compared with the PARP1 wild‐type counterpart in the 2D culture environment." (PMID 31989039, 2020). "Eventually, the compound ZINC20032678 effectively induced breast cancer cell apoptosis through inhibition of both c-Met and PARP-1 kinases activities." (PMID 32201536, 2020). "For example, PARP1 is known to be downstream of ER-dependent transcriptional response in breast cancer cells." (PMID 32455851, 2020). "Numerous clinical studies have indicated that inhibiting PARP-1 made great effort towards personalizing treatment in breast cancer." (PMID 32201536, 2020). "In the present study, we investigated this possibility by exploring the mechanisms of PARP1 reduction by nutlin-3a using the MCF-7 human breast cancer cell line." (PMID 32405340, 2020). "In summary, the results from our preclinical model confirmed the potential clinical value for synergizing KLF4 and PARP1 in TNBC breast cancer therapy." (PMID 33231937, 2020). "RNA sequencing data from The Cancer Genome Atlas showed that PARP-1 is overexpressed in ovarian and breast carcinoma compared to normal tissue." (PMID 33352773, 2020). "PARP‐1 contains three zinc‐binding (Zn) domains in its N‐terminus, a breast cancer one protein C‐terminal (BRCT) domain, and a tryptophan‐, glycine‐, arginine‐rich (WGR) domain at its centre, as well as a C‐terminal catalytic domain." (PMID 30804002, 2019). "In tamoxifen-resistant vs. -sensitive breast cancer cells, oxidative stress and PARP1 overexpression were increased." (PMID 30621214, 2019). "Single nucleotide polymorphisms in BER genes such as POL β, PARP1, and X-ray cross complementing protein 1 (XRCC1) are associated with increased risk of developing breast cancer." (PMID 31596905, 2019). "In breast cancer cells with BRCA1/2 mutations, the administration of PARP1 inhibitors would largely destroy the repair of damaged DNA by blocking the homologous recombination repair pathway, eventually leading to cell death." (PMID 30890936, 2019). "In this regard, our study reveals that both oxidative damage and PARP1 levels are elevated in ERα+ tamoxifen resistant breast cancer." (PMID 30621214, 2019). "Previous reports have described increased oxidative stress in tamoxifen resistant versus sensitive breast cancer and a role for PARP1 in mediating oxidative damage repair." (PMID 30621214, 2019). "We treated a panel of TNBC and ER+ human breast cancer cell lines and several mouse ER-negative cell lines with the two antagonists and two RORγ agonists along with the PARP-1 inhibitors for comparison." (PMID 31604910, 2019).
breast cancer (continued). "Our study shows a new mechanism that links PARP1 with the removal of DNA damage in breast cancer cells via the regulation of BRG1–EP300-dependent transcription of genes involved in DNA repair pathways." (PMID 31614656, 2019). "PARP1 activation via DNA damage is believed to play an important role in many diseases, including breast cancer and diabetic neuropathy." (PMID 31500199, 2019). "As such, it was of interest to investigate the mechanism by which PARP1 was overexpressed in tamoxifen resistant breast cancer cells." (PMID 30621214, 2019). "Based on overexpression of PARP1, we show co-administration of PARPi with tamoxifen decreases cell survival in ER+ breast cancer cells." (PMID 30621214, 2019). "There is evidence that PARP1 regulates estrogen-dependent breast cancer cell growth through the modulation of the estrogen receptor (ER)-insulin-like growth factor 1 receptor (IGF-1R)-Na(+)/H(+) exchange regulatory cofactor NHE-RF3 (PDZK1) axis." (PMID 30890936, 2019). "Examples of predictive methylated genes are MGMT in glioma (temozolomide), BRCA1 in breast cancer (PARP1 inhibitors, cisplatin, and chemotherapy), and PRKCDBP in colon cancer (oxaliplatin), among others." (PMID 29445424, 2018). "In another study, CDK1 dependent phosphorylation of PARP-1 displaced histone H1 from chromatin, thus accelerating progestin-mediated breast cancer cell proliferation." (PMID 29541423, 2018). "Increased PARP1 expression has been associated with decreased DFS and DDFS in other cancers, such as serous ovarian carcinoma and breast cancer." (PMID 29681762, 2018). "Enrichment analysis and experimental validation demonstrated that ADQ might improve breast cancer chemosensitivity via inhibiting caveolin-1, which further triggered expression changes of cell cycle-related proteins p21/cyclinB1 and apoptosis-associated proteins PARP1, BAX and Bcl-2." (PMID 30333750, 2018). "In our previous study of breast carcinoma and soft-tissue sarcomas, 51 (98/192) % and 56 (63/112) % were also included in the poor prognostic group expressing PARP1, respectively." (PMID 29784019, 2018). "A recent study showed the possibility of considering the overexpression of PARP1 and miR-151-5p as biomarkers useful to correctly treat sporadic breast cancers with PARPi." (PMID 28881597, 2017). "Poly(ADP-ribose) polymerase 1 (PARP1), a critical DNA repair protein, is frequently upregulated in breast tumors with a key role in breast cancer progression." (PMID 29212245, 2017). "The degree of cytotoxicity of PARP1 inhibitors was previously found to correlate with PARP1 expression levels, which are known to be increased in breast cancer." (PMID 29262611, 2017). "Rationally, PARP1 represents an attractive target for the development of new anticancer agents against breast cancer." (PMID 29212245, 2017). "Although overexpression of PARP1 is found in different primary human tumors, the biological and clinical significance of the protein in breast cancer has yet to be fully elucidated." (PMID 29029467, 2017). "Consistently, knockdown of endogenous RNF144A in human breast cancer MDA-MB-231 cells by specific short hairpin RNAs (shRNAs) targeting human RNF144A (shRNF144A) decreased the ubiquitination levels of endogenous PARP1 (compare lane 3 with 2)." (PMID 29212245, 2017). "Breast cancer cells with mutations in the BRCA1 and BRCA2 genes can display defects in DSBs repair in HRR pathway and inhibition of PARP1 (poly(ADP-ribose) polymerase 1), which is a crucial protein in SSBR, can result in death of these cells." (PMID 28718810, 2017). "To explore the interaction between autophagy and apoptosis in more detail, we detected the immunoblotting of LC3B, caspase-3 and PARP-1 of breast cancer cells with 3-MA pre-treatment before combined BEZ235 and TSA treatment, an inhibitor of autophagy." (PMID 28060760, 2017).
breast cancer (continued). "The ability of [125I]KX1 to measure PARP-1 expression in vivo was tested in mice bearing subcutaneous HCC1937 (high PARP-1) and MDA-MB-231 (low PARP-1) human breast cancer xenografts." (PMID 28058462, 2017). "Our data also showed that cleaved caspase-3, caspase-8, caspase-9 and poly ADP ribose polymerase-1 (PARP-1) were all increased in breast cancer cells." (PMID 28060760, 2017). "General well-investigated eligibilities of PARP1 inhibitors include ovarian and breast carcinomas, both BRCA-mutant and BRCA-proficient." (PMID 28991194, 2017). "One of the key variants is PARP-1 rs8679 which is 3′UTR region and reported to have binding site for has-miR-145 and it is reported to be associated with increased risk of breast cancer." (PMID 27746584, 2016). "One breast cancer study had found that miR-361 was overexpressed in PARP1-upregulating BRCA-germline mutated and sporadic breast cancers." (PMID 27959953, 2016). "In contrast to this Bai and Cantó reported that rs8679 does not have any correlation with PARP-1 expression; this is opposing our results, but they observed significantly higher expression of PARP-1 gene in breast cancer." (PMID 27746584, 2016). "Preclinical studies in breast cancer models showed that BRCA1 or BRCA2 deficient cell lines, when compared to BRCA proficient cell lines, are extremely sensitive to PARP1 inhibition." (PMID 27323902, 2016). "The recent finding that TGF-β sensitizes breast cancer cells to lethality in response to PARP1 inhibitors is fully compatible with our proposal." (PMID 27129221, 2016). "Breast carcinoma in the CSbbph-low group that corresponds to a CSddrm-low immunophenotype has a 95% 10-year rate, but the ten-year DSS rate of breast carcinoma with a BRCA1+/BRCA2+/PARP1+/γH2AX+ immunophenotype was 35%." (PMID 27643881, 2016). "They demonstrated that, breast cancer cells containing germ line mutations in BRCA1 and BRCA 2 genes become sensitized to PARP inhibitors in a PARP1 dependant manner and lose sensitivity to PARP inhibition on regaining BRCA2 functionality." (PMID 25606064, 2015). "Similar chromatin-dependent mechanisms with theparticipation of PARP1 are involved in the estrogen-dependent regulation ofgene expression in breast cancer (BC)." (PMID 26483957, 2015). "Of a total 131 breast cancer sera analyzed, 15.3% (20/131) was shown to have autoantibody to PARP1, 19.1% (25/131) was shown to have autoantibody to BRCA1, 36.6% (48/131) was shown to BRCA2." (PMID 25865228, 2015). "Increased PARP1 expression issometimes observed in melanomas, breast cancer, lung cancer, and otherneoplastic diseases." (PMID 26483957, 2015). "Immunohistochemistry indicated that Pathology Grade at diagnosis to PARP1 expression in breast cancer was different (P < 0.05)." (PMID 25865228, 2015). "Because this medulloblastoma had an oncogenic mutation in BRCA2 (6174delT), we also tested its in vitro response to a PARP1 inhibitor, thought to induce synthetic lethality in BRCA2-mutated breast cancer." (PMID 26380221, 2015). "CAFs have been shown to protect breast cancer cells against apoptosis induced by Doxorubicin and the PARP-1 inhibitor ABT-888." (PMID 25280402, 2014). "Breast cancer in vitro and in vivo studies have indicated that mild hyperthermia sensitizes cancer cells to PARP-1 inhibitors." (PMID 25202410, 2014). "For example, breast cancer cells with mutations in the BRCA1 and BRCA2 are sensitive to inhibition of poly [ADP-ribose] polymerase (PARP1), whereas inhibition of PARP1 has little influence on survival and proliferation of normal cells with WT BRCA." (PMID 24150935, 2014).
breast cancer (continued). "The PARP-1 Val762Ala (T2444C) rs1136410 SNP has been associated with a reduced ADP-ribosylation activity and cancer susceptibility and the PARP-1 3′ UTR rs8679 T > C SNP is associated with bladder and breast cancer risk." (PMID 25139788, 2014). "Our data indicated that lestaurtinib is a potent therapeutic agent for killing breast cancer cells and it amplifies the ability of the PARP1 inhibitor AG14361 to kill breast cancer cells irrespective to their BRCA1 status." (PMID 24962108, 2014). "Along this line, new therapeutic approaches targeting breast cancer which involve PARP1 have been proposed." (PMID 24243533, 2014). "When the effects of PARP1 over the PR were evaluated in breast cancer cells treated with progestin, there was an enhanced PARP1 enzymatic activity." (PMID 24243533, 2014). "In fact, Poly-ADP-ribose polymerase 1 (PARP1), which plays a signaling role in the DNA Base Excision Repair pathway (BER), is critical for viability of familial breast cancer cells deficient in HR proteins BRCA1 and BRCA2." (PMID 25185513, 2014). "In this line, PARP1 is involved in prostate and breast cancer, by means of modulating AR and PR respectively." (PMID 24243533, 2014). "In the present study on gene expression profile, mean PARP1 expression was significantly higher in breast cancer relative to normal breast tissue." (PMID 24392019, 2013). "This study reports a comprehensive analysis of the BRCA/53BP1/PARP-1 factors of DNA repair in the largest cohort of patients with sporadic breast cancer to date." (PMID 24191908, 2013). "In a recent meta-analysis carried out in a large public retrospective gene expression dataset, revealed that PARP-1 messenger RNA (mRNA) was overexpressed in breast cancer." (PMID 24392019, 2013). "Gene expression patterns were quantified to investigate the PARP1 expression levels in breast cancer samples and controls." (PMID 24392019, 2013). "Another putative PARP1 inhibitor, Iniparib (Sanofi-Aventis) was reported to be a non-competitive inhibitor that made it through Phase I and Phase II clinical trials for breast cancer, but it eventually failed a Phase III trial." (PMID 24202319, 2013). "PARP1 has roles in DNA damage response, reinitiation of stalled replication forks and is up-regulated in many cancers including breast cancer." (PMID 23785396, 2013). "Expression of PARP1 is significantly higher in breast cancer compared to 'normal'/benign breast tissue samples (P < 0.001)." (PMID 24392019, 2013). "We have also observed that PARP1 Val762Ala is associated with the Age, PR status, HER2 status and breast cancer susceptibility in Saudi population." (PMID 24392019, 2013). "In the present study, we found a significant variation in the distribution of PARP1 rs1136410 genotypes between breast cancer cases and the matched healthy controls (p > 0.05)." (PMID 24392019, 2013). "The inhibitory activity of different anticancer metal complexes based on platinum, ruthenium, and gold metal ions was evaluated on the zinc-finger protein PARP-1, either purified or directly on protein extracts from human breast cancer MCF7 cells." (PMID 21804822, 2011). "Gene expression profiling performed primarily on breast cancer samples from 50 patients showed that PARP-1 expression was significantly upregulated (P <0.0001)." (PMID 21050422, 2010). "PIK3R1 and PLCG1 are involved in intracellular signaling cascades and their differential regulation is known to be involved in tumorigenesis, while POU2F1 interacts with several known breast cancer-associated proteins (i.e. BRCA1, BARD1 and PARP1)." (PMID 17280605, 2007). "Studying HR-proficient MCF7 breast cancer cells, we confirmed a role for PARP1 in promoting DSB repair and limiting resection stress and identified the hexosamine biosynthetic pathway (HBP)-dependent post-translational modification O-GlcNAcylation as an independent regulator." (PMID 41778489, 2026).
breast cancer (continued). "Furthermore, nuclear PARP1 overexpression has been observed in various breast cancers, including ductal and highly malignant triple-negative breast carcinomas, and even in breast cancer stem cells." (PMID 40149342, 2025). "Consequently, high levels of nuclear PARP1 correlate with poor prognosis, contributing to lower disease-free and overall survival rates in breast cancer patients." (PMID 40149342, 2025). "We may suggest that PARP‐1 inhibition increased oxidative DNA damage only in breast cancer cells expressing Ets‐1." (PMID 39778077, 2025). "With further advancements in computational and experimental methods, synergy between these fields will drive the development of next-generation PARP1 inhibitors, promoting revolutionary targeted cancer treatments and improved prognosis for breast cancer patients worldwide." (PMID 41304924, 2025). "In addition to breast cancer, PARP‐1 is overexpressed and the PARylation level is increased in various other cancers, such as ovarian and colorectal cancers, thereby promoting tumor progression." (PMID 39778077, 2025). "Similarly, in breast cancer patients, a high cytoplasmatic expression of PARP-1 correlates with aggressivity and predicts sensitivity to chemotherapy and prognosis." (PMID 39858519, 2025). "Furthermore, it has been reported that HMGA2 acts as a functional antagonist of PARP1 inhibitors in breast cancer cell lines." (PMID 38778348, 2024). "PARPi such as olaparib, the first FDA-approved PARPi for the treatment of BRCA-mutant HR-deficient breast cancer, are NAD+ analogs whose mechanism of action relies on the catalytic inhibition of PARP1, PARP2, and other PARP enzymes via their binding to the NAD+-binding site." (PMID 39201277, 2024). "It appeared plausible that PARP-1 may regulate the influence of TNF-α on breast cancer metastasis through the NF-κB signalling pathway." (PMID 39201718, 2024). "Similarly, upregulation of PARP1 by SNAIL in MDA-MB-231 breast cancer cell lines contributes to resistance against doxorubicin." (PMID 38413011, 2024). "PARP1 upregulation has been reported in several malignancies, including oral cancer, ovarian cancer, testicular tumors, neuroblastoma, malignant lymphoma, breast cancer, colon cancer, endometrial cancer, and BRCA-mutated ovarian cancer." (PMID 39200230, 2024). "In addition, PARP1 expression is upregulated in about 70% of primary breast cancers, especially TNBC." (PMID 39679370, 2024). "PARP1/2 inhibitors could be used as drugs in breast cancer treatment through a mechanism known as synthetic lethality." (PMID 39057953, 2024). "Furthermore, PARP1 expression varies across breast cancer subtypes: HER2-positive and TNBC show higher nuclear expression, whereas luminal subtypes display increased cytoplasmic and overall expression." (PMID 39768978, 2024). "Compound 3 increased PARP1 cleavage and apoptosis of breast cancer cells." (PMID 38791105, 2024). "Furthermore, the model established by SVR with triple kernel function shows 8 important factors that have a great influence on the biological activity of PARP1 inhibitors, which will guide new drug design and screening for breast cancer." (PMID 38370471, 2024). "Additionally, the studies examining PARP-1 in locally advanced breast cancer and pancreatic cancer were relatively small, bringing into question its generalizability to another cancer population such as UC." (PMID 38675715, 2024). "snoRNAs may be potential regulators of breast cancer cell growth via PARP-1’s catalytic activity, providing alternative therapeutic action without the DNA damage activation of PARP-1." (PMID 39795985, 2024). "Therefore, this study focused on the value of the DNA repair gene PARP1 and NF-κB pathway proteins in predicting the postoperative metastasis of breast cancer." (PMID 38388665, 2024).